SHANK1 (SH3 and multiple ankyrin repeat domains 1)
Diseases named in the same sentence as SHANK1 in open-access papers (continued):
Sharing a sentence is not in itself a finding about the gene and the disease.
chronic lymphocytic leukemia (2 papers, 2019 to 2022). "Methylation alteration at this SHANK1 CpG island is used as a biomarker for risk and diagnosis of chronic lymphocytic leukemia." (PMID 35468874, 2022). "It has also been reported that the methylation alteration of SHANK1 could serve as a predictive, diagnostic, and prognostic biomarker for chronic lymphocytic leukemia." (PMID 35468874, 2022).
lung carcinoma (2 papers, 2020 to 2022). "A549 and H1299 lung cancer cell lines were chosen to investigate the role of SHANK1 in cell proliferation, migration, and apoptosis." (PMID 35468874, 2022). "SHANK1 bound with KL and MDM2, and downregulated KL by ubiquitin degradation, and it promoted the migration, invasion, and proliferation abilities of lung cancer cells." (PMID 35468874, 2022). "Overall, SHANK1 expression was significant in its negative correlation with KL expression in lung cancer tissue." (PMID 35468874, 2022).
Alzheimer disease (1 paper, 2025). A progressive, neurodegenerative disease characterized by loss of function and death of nerve cells in several areas of the brain leading to loss of cognitive function such as memory and language. "Bioinformatics analysis revealed that the expression of SHANK1 was reduced across various brain regions, including the frontal cortex (FC), temporal cortex (TC), and hippocampus (HP) in Alzheimer's disease (AD), based on the GSE36980 dataset." (PMID 40574425, 2025). "Since the GSE36980 dataset lacks detailed clinical and pathological data on Alzheimer's disease patients, we are unable to directly assess the correlation between SHANK1 and clinical disease severity within this dataset." (PMID 40574425, 2025). "Correlation analysis in GSE84422 reveals a negative association between SHANK1 expression and both neurofibrillary tangle density and clinical dementia rating, suggesting a potential link between SHANK1 levels and disease severity in Alzheimer's disease." (PMID 40574425, 2025).
colon cancer (1 paper, 2022). "Recently, it was reported that SHANK1 was highly expressed in colon cancer, and that such patients were more likely to receive a more severe prognosis." (PMID 35468874, 2022). "SHANK1 is abnormally and highly expressed in colon cancer; knockdown of SHANK1 inhibits the survival, proliferation, and migration of colon cancer cells through the AKT/mTOR signaling pathway." (PMID 35468874, 2022). "The knockdown of SHANK1 inhibited viability and induced apoptosis in colon cancer cell lines through AKT/mTOR signaling pathways." (PMID 35468874, 2022).
COVID-19 (1 paper, 2024). A disease caused by infection with severe acute respiratory syndrome coronavirus 2. "SHANK1, downregulated in COVID-19 patients, facilitates protein-protein interactions in excitatory synapses, and its downregulation may hinder neuronal communication." (PMID 38760690, 2024).
memory impairment (1 paper, 2025). "This study is the first to report on the dysfunction of the PKA/CREB/SHANK1 axis in HS diet‐induced learning and memory impairments, suggesting that enhancing PKA activity to increase SHANK1 levels may represent a promising therapeutic approach for treating HS‐induced cognitive dysfunction." (PMID 40574425, 2025).
migraine (1 paper, 2023). "Associations between SLC17A8, SHANK1, TRPV1, TRPV3 and TRPM8 gene polymorphisms and the risk of migraine by aura." (PMID 37303955, 2023). "Further, we found one novel SHANK1 rs3745521 was associated with migraine with aura risk, and two novel SNPs (rs11110359 and rs11568537 of SLC17A8 gene) were associated with the susceptibility of migraine without aura risk." (PMID 37303955, 2023).
non-Hodgkin lymphoma (1 paper, 2021). Distinct from Hodgkin lymphoma both morphologically and biologically, non-Hodgkin lymphoma (NHL) is characterized by the absence of Reed-Sternberg cells, can occur at any age, and usually presents as a localized or generalized lymphadenopathy associated with fever and weight loss. "Among cancer cell lines transcript expression for SHANK1 was highest in NCI-H1930 (lung), 143B (osteosarcoma) and SUDHL1 (non-Hodgkin’s lymphoma)." (PMID 33836029, 2021).
non-small cell lung carcinoma (1 paper, 2022). A group of at least three distinct histological types of lung cancer, including non-small cell squamous cell carcinoma, adenocarcinoma, and large cell carcinoma. "In the present study, we report that the expression of SHANK1 is upregulated in non-small cell lung cancer (NSCLC), and is correlated with clinic pathological characteristics of NSCLC." (PMID 35468874, 2022).
Obesity (1 paper, 2025). Accumulation of substantial excess body fat. "A double knockout of Shank1 and Shank2 in mice has shown a significant reduction in the activation levels of the Akt signaling pathway, which is one of the primary signaling pathways involved in the pathogenesis of T2D and associated obesity." (PMID 41465472, 2025).
Sepsis (1 paper, 2024). Sepsis is defined as life-threatening organ dysfunction caused by a dysregulated host response to infection. "It was noted that several genes with DRE were previously reported or implicated to play a role in sepsis or SAE, such as superoxide dismutase 2 (SOD2), Miat, peptidylarginine deiminase 2 (Padi2), Shank1, transcription factor 4 (Tcf4) and kinesin family member 3 (Kif3c)." (PMID 39135964, 2024).
cancer (9 papers, 2016 to 2026). A tumor composed of atypical neoplastic, often pleomorphic cells that invade other tissues. "Other SHANK1-associated CGIs are reportedly differentially methylated in other cancers, and they have been proposed as tumor biomarkers." (PMID 31452839, 2019). "The most plausible scenario would be that methylation changes in different SHANK1-associated CGIs would be related to different types of cancer, thus serving as specific signatures for different types of tumors." (PMID 31452839, 2019). "SHANK1 may play tumor-associated roles in the development of malignant neoplasm." (PMID 27768594, 2016). "Benign versus malignant comparisons identified 101 differentially methylated CpGs, including hypermethylated CpG in BAIAP2L1 and hypomethylated CpG in SHANK1 in malignant tumors." (PMID 41597272, 2026). "About five-fold more cancer samples exhibit SHANK2 amplification compared to SHANK1 and SHANK3." (PMID 32661924, 2021). "In contrast, some of the genes, including ENTHD1, HELZ2, PCDH12, CPNE4, and SHANK1, that are mutated in metastatic ACCs alone are completely novel and have not been functionally characterized in any cancer type until now." (PMID 30301885, 2018). "The results indicate that Shank1 knocking down could inhibit the proliferation of cancer cells." (PMID 35468874, 2022). "Transcript expression patterns for SHANK1, UBR3, and BSN in cancer cell lines and Clontech’s normal human tissue panels were analysed using qPCR, detection of the exon encoding the cross-reactive peptide." (PMID 33836029, 2021).
neurodevelopmental disorder (5 papers, 2023 to 2025). A behavioral and cognitive disorder with onset during the developmental period that involves impaired or aberrant development of intellectual, motor, or social functions. "Variants in ASD-associated genes (CHD8, FOXP1, and SHANK1) and genes linked to other neurodevelopmental disorders (CDH15, GATAD2B, and SHROOM4) were also detected." (PMID 40642607, 2025). "In other studies, the region of CLEC11A has been identified as a candidate locus for the etiology of neurodevelopmental disorders due to its position nearby SHANK1, a gene strongly associated with ASD." (PMID 37012247, 2023).
tumor (4 papers, 2016 to 2026). "While global methylation changes do not consistently predict transcriptional output, locus-specific effects, notably in DSCAML1, BAIAP2L1, and SHANK1, suggest potential mechanistic relevance and potential functional impact on tumor biology." (PMID 41597272, 2026). "We report that SHANK1 is an oncogene involved in cell proliferation, apoptosis, transformation, invasion, and tumor progression in NSCLC." (PMID 35468874, 2022). "Fifty out of 100 NSCLC tumor tissues showed abnormally high expression of SHANK1, significantly higher than that of their corresponding adjacent normal lung tissues." (PMID 35468874, 2022). "To investigate the impact of SHANK1-associated CGI hypermethylation on gene expression, we tested the gene expression level of SHANK1 in 27 CLL cases and 16 non-tumor subjects by qRT-PCR." (PMID 31452839, 2019). "Overall, our results suggest methylation alteration at this SHANK1 CpG island as a biomarker for risk and diagnosis of CLL, and also in the personalized quantification of tumor aggressiveness." (PMID 31452839, 2019). "Four tumor tissues presented high expression of SHANK1, but with low expression of KL." (PMID 35468874, 2022). "In contrast, two tumor tissues presented low expression of SHANK1, but high expression of KL." (PMID 35468874, 2022). "Mouse cell-derived xenograft model also confirmed the effects of SHANK1 on tumor growth in vivo." (PMID 35468874, 2022). "The results show that SHANK1 was overexpressed in tumor tissue samples." (PMID 35468874, 2022). "Furthermore, we found that SHANK1 increases the protein degradation of Klotho (KL), an important tumor suppressor, through ubiquitination-dependent pathway." (PMID 35468874, 2022). "In summary, our results suggest SHANK1 as a promising tumor biomarker for CLL early diagnosis." (PMID 31452839, 2019). "Therefore, SHANK1 methylation might be a useful molecular biomarker in the personalized quantification of tumor aggression in CLL." (PMID 31452839, 2019). "On the other hand, tumor samples with a high lymphocyte count, showed a high CD19+ B-cells contribution and higher SHANK1 methylation values, compared to samples with low CD19+ B-cells contribution." (PMID 31452839, 2019). "Inference of cell type contributions on tumor whole blood samples revealed that there was a strong positive correlation between CD19+ B-cells contributions and SHANK1 methylation values." (PMID 31452839, 2019). "Our results showed that HBx could increase H3K9me3 enrichment on genes of SHANK1 and SLC16A3, this might contribute to modulation of tumor-immune cell interactions." (PMID 27768594, 2016).
psychiatric disorder (1 paper, 2021). A disorder characterized by behavioral and/or psychological abnormalities, often accompanied by physical symptoms. "In patients suffering from psychiatric disorders, Shank1/2/3 at excitatory synapses are frequently mutated." (PMID 34198779, 2021).
SHANK1 also shares sentences with these, for which no sentence is quoted: neurological diseases (3 papers); depression (2); bipolar disorder (1); brain disorder (1); cocaine addiction (1); cognitive decline (1); Cornelia de Lange syndrome (1); dementia (1); Down syndrome (1); genetic disorders (1); Mild intellectual disability (1); neuroblastoma (1); osteosarcoma (1); Parkinson’s (1); Phelan-McDermid syndrome (1); psychosis (1); spinal muscular atrophy (1); tuberous sclerosis (1).